KIF14 (kinesin family member 14)
Diseases named in the same sentence as KIF14 in open-access papers (continued):
Sharing a sentence is not in itself a finding about the gene and the disease.
prostate carcinoma (9 papers, 2017 to 2025). A carcinoma that arises from epithelial cells of the prostate gland. "The microtubule motor protein KIF14 has also been reportedly linked to poor patient outcomes and disease progression in individuals with prostate cancer." (PMID 36245556, 2022). "For example, KIF14 was found to contribute to chemoresistance in advanced prostate cancer through the activation of AKT." (PMID 40374610, 2025). "Based on analysis on two datasets derived from samples of patients with PCa, we determined that KIF14 is highly overexpressed in prostate carcinoma as compared with normal prostate tissues." (PMID 28525372, 2017). "In this study, we identified KIF14 as a potential candidate oncogene involved in tumor progression and poor prognosis in prostate cancer." (PMID 28525372, 2017). "In addition to that, KIF14 promotes tumor invasiveness and correlates with poor prognosis in prostate cancer." (PMID 37175004, 2023). "We examined whether reduced KIF14 expression would affect prostate cancer cell growth by counting the cell numbers for three constitutive days after siRNA transfection." (PMID 28525372, 2017). "Taken together, these data indicate that KIF14 overexpression is necessary for G2/M cell cycle progression, promotion of cell proliferation, and prevention of cell apoptosis, which ultimately leads to indefinite growth of prostate cancer cells." (PMID 28525372, 2017). "All these further support our finding that KIF14 is a functional oncoprotein in prostate cancer." (PMID 28525372, 2017). "Knockdown of KIF14 in DU145 and PC3 prostate cancer cells suppressed cell proliferation, induced cell cycle arrest and apoptosis." (PMID 28525372, 2017). "Knockdown of KIF14 in DU145 and PC3 prostate cancer cells reduced cell proliferation, induced cell cycle arrest and apoptosis." (PMID 28525372, 2017). "However, the role of KIF14 in prostate cancer remains unknown yet." (PMID 28525372, 2017). "However, the expression of KIF14 and its role in prostate carcinoma remain unclear thus far." (PMID 28525372, 2017). "Furthermore, relative to the non-castration-resistant prostate cancer cell line (LNCaP), the expression of KIF14, CENPE, KIF15, KIF18B, and KIFC1 was significantly elevated in the castration-resistant PCa cell line (DU145)." (PMID 40956849, 2025). "However, the expression of KIF14 and its role in prostate carcinoma has not been reported thus far." (PMID 28525372, 2017).
cervical carcinoma (8 papers, 2016 to 2025). A carcinoma arising from either the exocervical squamous epithelium or the endocervical glandular epithelium. "KIF14 is an oncogene in cervical cancer, and knocking down KIF14 causes cell cycle arrest by inhibiting p27 degradation, thus affecting cell viability, proliferation, and migration." (PMID 35439960, 2022). "KIF14 has been associated with cervical cancer, and a knockdown model of KIF14 impacted the cell cycle by affecting cell viability, proliferation, and migration, thus placing it as a potential therapeutic target." (PMID 36362378, 2022). "In conclusion, our study showed that KIF14 was up-regulated and was significantly associated with chemoresistance in cervical cancer." (PMID 27128470, 2016). "Moreover, Cox proportional hazards risk analysis demonstrated that KIF14 was an independent prognostic factor for chemoresistance in cervical cancer." (PMID 27128470, 2016). "Collectively, our findings reveal the functional mechanism by which KIF14 regulates the cell cycle during tumorigenesis, thus providing potential value in the treatment of cervical cancer." (PMID 35439960, 2022). "Interfering with KIF14 expression significantly inhibited the migration and invasion of cervical cancer cells." (PMID 35439960, 2022). "Kinesin family member 14 (KIF14) expression levels were linked to chemosensitivity of hepatocellular carcinoma and cervical cancer, as well as to prognosis of various cancers, such as breast and pancreatic cancer." (PMID 35884419, 2022). "The effect of KIF14 overexpression on cervical cancer cells was further studied, and we first verified the overexpression efficiency in HeLa and siHa cells." (PMID 35439960, 2022). "Next, to explore the role of KIF14, we designed and synthesized three interference sequences targeting KIF14 and transiently transfected HeLa and SiHa cervical cancer cells." (PMID 35439960, 2022). "RT–qPCR showed that the KIF14 level was upregulated in 20 cervical cancer tissues compared to 10 normal tissues." (PMID 35439960, 2022). "In conclusion, the KIF14 level is upregulated in cervical cancer, and KIF14 knockdown suppresses cell proliferation, migration, and invasion, resulting in cell cycle arrest by inhibiting p27 degradation." (PMID 35439960, 2022). "A study reported the high levels of KIF14 expression in cervical carcinoma cell line C-33A.KIF14 overexpression was also correlated with poor prognosis, tumor aggressiveness, lymph node metastasis and resistance to paclitaxel treatment." (PMID 29312619, 2017). "In the present study, we assessed KIF14 expression in cervical cancer specimens and paired adjacent normal tissues as well as its expression in tissues samples from patients who are sensitive or resistant to paclitaxel treatment." (PMID 27128470, 2016). "Kaplan–Meier analysis and Cox proportional hazards model were applied to assess the correlation between KIF14 expression levels and overall survival (OS) of cervical cancer patients." (PMID 27128470, 2016). "KIF14 expression levels were also measured in tissue samples from a different population of participants consisting of 56 cervical cancer patients who are sensitive to paclitaxel treatment and 53 patients who are resistant to paclitaxel treatment." (PMID 27128470, 2016). "Here, we verified the role and regulatory mechanism of KIF14 in cervical cancer." (PMID 35439960, 2022). "Therefore, this study aimed to observe KIF14 expression in cervical cancer and further explore the influence of changes in its expression on the proliferation, invasion, migration, and cycle of cervical cancer cells." (PMID 35439960, 2022). "In this study, the KIF14 level in cervical cancer tissue was significantly upregulated." (PMID 35439960, 2022). "In addition, KIF14 knockdown promotes malignancy in cervical cancer cells by inhibiting p27 degradation, resulting in cell cycle arrest." (PMID 35439960, 2022).
cervical carcinoma (continued). "Clone formation and Transwell assays suggested that KIF14 overexpression could significantly promote the proliferation, migration, and invasion of cervical cancer cells." (PMID 35439960, 2022). "However, our current results revealed a biological role for KIF14 in cervical cancer pathogenesis and provided new ideas for CC diagnosis and therapy." (PMID 34495250, 2021). "Therefore, our findings indicated the biological function of KIF14 in cervical cancer and provided new ideas for CC diagnosis and therapies." (PMID 34495250, 2021). "KIF14 may serve as a predictor of poor survival and a novel prognostic biomarker of chemoresistance to paclitaxel treatment in cervical cancer." (PMID 27128470, 2016). "KIF14 may serve as a novel predictive factor for poor survival and a prognostic biomarker for chemoresistance in cervical cancer." (PMID 27128470, 2016). "Our study suggests that KIF14 may serve as a predictor of poor survival and a novel prognostic biomarker of chemoresistance to paclitaxel treatment in cervical cancer." (PMID 27128470, 2016). "Therefore, this study aimed to analyze the possible relationship between KIF14 and cervical cancer." (PMID 35439960, 2022). "In addition, the KIF14 level in cervical cancer cells was higher than that in cervical cells." (PMID 35439960, 2022). "Therefore, we concluded that KIF14 was upregulated in cervical cancer." (PMID 35439960, 2022). "We first evaluated the expression levels of KIF14 in 47 pairs of cervical cancer tissues and the NATs from patients who had not been exposed to any chemotherapy using quantitative real-time PCR." (PMID 27128470, 2016). "KIF14 expression levels were significantly increased in cervical cancer tissues compared with matched non-cancerous tissues and it was higher in tissues of patients who are chemoresistant compared with those who are chemosensitive." (PMID 27128470, 2016). "However, the expression of KIF14 and its potential prognostic significance have not been investigated in cervical cancer." (PMID 27128470, 2016). "However, the expression of KIF14 and its clinical significance has not been investigated in cervical cancer." (PMID 27128470, 2016).
hepatocellular carcinoma (8 papers, 2013 to 2025). A malignant tumor that arises from hepatocytes. "It was reported that in hepatocellular carcinoma, loss of KIF14 downregulates the expression of Skp2 and Cks1, leading to accumulation of p27Kip1." (PMID 28525372, 2017). "For example, it was observed that the expression of KIF14 was elevated in sorafenib-resistant hepatoma cell lines, HepG2 and Huh7, in which sorafenib treatment had a much lessened inhibitory effect on KIF14 relative to parent cells." (PMID 38433242, 2024). "It has been reported that knockdown of KIF14 interferes with cell cycle progression and cytokinesis by blocking the p27 (Kip1) ubiquitination pathway in hepatocellular carcinoma." (PMID 27128470, 2016).
triple-negative breast carcinoma (8 papers, 2014 to 2026). An invasive breast carcinoma which is negative for expression of estrogen receptor (ER), progesterone receptor (PR), and human epidermal growth factor receptor 2 (HER2). "More recently, KIF14 has been identified as a regulator of doxetaxel chemosensitivity in triple-negative breast cancer." (PMID 27128470, 2016). "Further studies indicated that up-regulation of KIF14 contributes to chemoresistance by promoting phosphorylation of AKT in triple-negative breast cancer." (PMID 27128470, 2016). "More recently, KIF14 has been reported to be involved in regulating chemoresistance by phosphorylating AKT in triple-negative breast cancer." (PMID 27128470, 2016). "The effect of KIF14 on AKT phosphorylation was also reported in triple-negative breast cancer." (PMID 28525372, 2017). "KIF14 can also promote AKT phosphorylation and contribute to chemoresistance in triple-negative breast cancer therapy." (PMID 34699322, 2021). "KIF14 activates AKT signaling, which contributes to chemoresistance of triple negative breast cancer." (PMID 28061449, 2017). "We had previously shown that KIF14, a protein-protein interactor of RIP2, is significantly over-expressed in triple-negative breast cancer." (PMID 24642040, 2014). "Interestingly, KIF14 and TLN-1 inhibition was found to sensitize triple-negative breast cancer (TNBC) cells to therapeutic intervention." (PMID 26822056, 2016). "In addition, kinesin family member 14 (KIF14) and TLN-1 expression levels predict a better outcome after cytotoxic chemotherapy, and inhibition of these genes sensitizes triple-negative breast cancer (TNBC) cells to therapeutic intervention." (PMID 26822056, 2016).
lung adenocarcinoma (7 papers, 2013 to 2024). A carcinoma that arises from the lung and is characterized by the presence of malignant glandular epithelial cells. "In this study, using loss of heterozygosity and array comparative genomic hybridization analyses, we observed a 30% loss in the regions surrounding KIF14 on chromosome 1q in lung adenocarcinomas." (PMID 23626713, 2013). "Taken together, these results suggest that KIF14 might have a greater loss (∼30%) than gain (3–6%) in lung adenocarcinomas." (PMID 23626713, 2013). "Kinesin family member 14 (KIF14) was up-regulated in a variety of cancers, including lung adenocarcinoma." (PMID 36497343, 2022). "GSEC/TYMSOS inhibited miR-101-3P to increase KIF14 expression in lung adenocarcinoma to promote immune checkpoint-related gene expression, immune cell biomarkers, and tumor immune cell infiltration." (PMID 36497343, 2022). "The overexpression of KIF14 in lung adenocarcinoma cells inhibited anchorage-independent growth in vitro and xenograft tumor growth in vivo." (PMID 23626713, 2013). "We next examined the expression of KIF14 in tissue specimens and adjacent normal tissues from 122 lung adenocarcinomas using immunohistochemistry." (PMID 23626713, 2013). "The results from 122 lung adenocarcinomas showed that 29 of the 63 patients with low KIF14 protein expression had cancer metastasis." (PMID 23626713, 2013). "In conclusion, the down-regulation of KIF14 occurred in 30% of lung adenocarcinomas, and the expression of KIF14 was negatively correlated with clinical outcomes in the lung adenocarcinoma patients examined in this study." (PMID 23626713, 2013). "To extend our analysis to protein expression levels, we used immunohistochemistry to examine the expression of KIF14 in tumor specimens from 122 lung adenocarcinoma patients in an independent cohort." (PMID 23626713, 2013). "However, the expression, prognosis, mechanism, and tumor immune regulation of KIF14 in lung adenocarcinoma (LUAD) remain obscure." (PMID 36227151, 2022). "Expression of KIF14 in lung adenocarcinoma in PrognoScan database." (PMID 36227151, 2022). "However, it can be seen from our analysis that KIF14 is highly expressed in SCLC cancer tissues, reminding us that we can distinguish lung adenocarcinoma from SCLC by the level of KIF14 expression." (PMID 34712733, 2021). "In this study, we evaluated the potential role of KIF14 in lung adenocarcinoma using loss of heterozygosity (LOH) and array comparative genomic hybridization (CGH) analyses of 138 lung adenocarcinomas in chromosome 1q, which is where KIF14 is located." (PMID 23626713, 2013). "In addition, we also examined the protein expression of KIF14 in tissue specimens from 122 lung adenocarcinoma patients using immunohistochemical staining." (PMID 23626713, 2013). "Because these data indicated that the expression of KIF14 could affect the migratory and invasive abilities of lung adenocarcinoma cell lines, we further investigated whether cell adhesion was affected after modulating KIF14." (PMID 23626713, 2013). "Our observations supported the hypothesis that KIF14 acts as a tumor suppressor in lung adenocarcinoma." (PMID 23626713, 2013). "To confirm the results obtained from the CL cells, we examined the KIF14 expression levels in other lung adenocarcinoma cell lines and overexpressed KIF14 in A549 cells with low endogenous KIF14 protein and silenced KIF14 in H1299 cells with relative high KIF14 protein levels." (PMID 23626713, 2013). "The results obtained in the present study showed that KIF14 might regulate cell migration and adhesion through associations with CDH11 and MCAM; this increase in the membrane localization of CDH11 in lung adenocarcinoma cell lines is a novel finding with regard to the function of KIF14." (PMID 23626713, 2013).
lung adenocarcinoma (continued). "In addition, the protein expression levels of KIF14 in 122 lung adenocarcinomas also indicated that approximately 30% of adenocarcinomas showed KIF14 down-regulation compared with the expression in the bronchial epithelial cells of adjacent normal counterparts." (PMID 23626713, 2013). "Therefore, KIF14 might act as a metastatic suppressor in lung adenocarcinoma." (PMID 23626713, 2013). "Therefore, KIF14 might be a potential target for lung adenocarcinoma treatment." (PMID 23626713, 2013). "Thus, KIF14 might inhibit tumor growth and cancer metastasis in lung adenocarcinomas." (PMID 23626713, 2013). "The array CGH and KIF14 protein expression in lung adenocarcinomas and adjacent normal bronchial epithelia." (PMID 23626713, 2013). "To examine this hypothesis further, we first assessed the endogenous KIF14 protein expression in low-invasive CL1-0 and high-invasive CL1-5 lung adenocarcinoma cells." (PMID 23626713, 2013).
pancreatic cancer (7 papers, 2013 to 2025). "In the present study, we aimed to determine the utility of KIF11 and KIF14 as markers of pancreatic cancer prognosis by analyzing the in-house IHC data and RNA-seq-based publicly available datasets in relation to clinicopathological traits and overall survival." (PMID 34208606, 2021). "High KIF14 mRNA expression is documented in many cancers including hepatocellular and laryngeal carcinomas, while KIF14 expression levels correlate with adverse features in papillary renal tumors and pancreatic carcinomas." (PMID 25528264, 2014). "Furthermore, KIF11 and KIF14 mRNA levels were strongly correlated with one another in pancreatic tumor samples from the TCGA cohort, which could be also observed in our functional enrichment." (PMID 34208606, 2021). "Furthermore, knockdown of KIF14 increased invasiveness and resistance to anoikis of T3M4 pancreatic cancer cells." (PMID 34208606, 2021). "In more detail, KIF14 was found to be strongly expressed in PDAC cells that did not invade nerves, whereas it was downregulated in those that did, as well as in non-invasive vs. neuroinvasive pancreatic carcinoma cell lines." (PMID 34208606, 2021).
medulloblastoma (6 papers, 2013 to 2025). A malignant, invasive embryonal neoplasm arising from the cerebellum. "In addition, it is also reported that expression of Kif14 is up-regulated in the cerebeller granule cell-derived medulloblastoma." (PMID 23308235, 2013).
colon cancer (4 papers, 2017 to 2024). "The top 50 genes that were positively correlated (upregulated DEGs; uDEGs) with KIF11 or KIF14 in colon cancer tissues were determined using TCGA dataset and the UALCAN web-based tool." (PMID 34575892, 2021). "KIF11, together with KIF14, another kinesin involved in the correct cell division, could be responsible for the pathological genomic instability of colon cancer, and their levels reflect the clinical outcome." (PMID 38939361, 2024). "To do so, we quantitatively determined the levels of the TNMD, MTHFD1L, and KIF14 proteins in healthy primary mammary epithelial cells (PMECs), a TNBC cell line (MDA-MB-231), and a colon cancer cell line (CT-26)." (PMID 39409999, 2024). "As in colon cancer, also in PAC the expression of KIF11 and/or KIF14 could be identified as a discrimination marker between patients with better and worse overall survival, independently of other relevant clinical risk factors." (PMID 38939361, 2024).
esophageal squamous cell carcinoma (4 papers, 2020 to 2023). Esophageal squamous cell carcinoma (ESCC) is a type of esophageal carcinoma (EC) that can affect any part of the esophagus, but is usually located in the upper or middle third. "In ESC, downregulating KIF14 inhibited esophageal squamous cell carcinoma cell proliferation, invasion, migration, and angiogenesis." (PMID 37504265, 2023). "It has also been found that downregulation of KIF14 expression can significantly inhibit the proliferation of esophageal squamous cell carcinoma cells and arrest the cell cycle in the G0/G1 phase." (PMID 32546690, 2020).
brain tumors (3 papers, 2021 to 2025). "Besides PRUNE_1, the other five genes (i.e., KIF11, KIF14, ASPM, CDK6, and ATR) have been reported as mutated in hereditary MCPH and overexpressed in primary brain tumors (e.g., MB)." (PMID 34745995, 2021). "In conclusion, inhibition of KNL1, CENPE, ASPM, CITK, and KIF14 may mimic the effects of MTAs on cell division but could work with particular effectiveness on brain tumor cells, underscoring the importance of developing specific inhibitors and test them in clinical trials." (PMID 34663805, 2021).